MYC (MYC proto-oncogene, bHLH transcription factor)
Diseases named in the same sentence as MYC in open-access papers (continued):
Sharing a sentence is not in itself a finding about the gene and the disease.
cancer (continued). "Our results demonstrate that MYC disruption of the molecular circadian clock releases metabolic and biosynthetic processes from circadian control, which may provide a distinct advantage to cancer cells." (PMID 37639465, 2023). "Besides, emerging studies have suggested the compelling function of MYC in cancer lipid metabolism." (PMID 37151387, 2023). "Thus, identifying pairs of synergistic vulnerabilities which are effective against MYC‐driven cancers may result in prolonging therapeutic durability and increasing the response rate." (PMID 36684069, 2023). "However, research illustrated that SUMOylation of MYC also mediated its oncogene activity and inhibition of SUMOylation might be a possible therapy for MYC-elicited cancers." (PMID 37415251, 2023). "Besides, we found that silencing of c-MYC could abrogate NEK8-mediated increase in cancer cell proliferation, cellular ATP, and DNA replication." (PMID 37596667, 2023). "Consequently, changes in MYC’s expression are directly correlated to cancer development." (PMID 36979947, 2023). "Therefore, appropriate inhibition or activation of these transformation-associated targets may contribute to interfering with the growth and viability of MYC-driven cancer cells." (PMID 36969025, 2023). "Additionally, CBL0137 antagonizes multiple other targets important for cancer processes, like MYC." (PMID 37974213, 2023). "Thus, targeting MYC appears as an attractive strategy for cancer therapies." (PMID 37519063, 2023). "Hence, a deeper understanding of the post-translational modification of MYC might provide novel and effective therapeutic strategies for cancer patients." (PMID 37596667, 2023). "It is suggested that increasing heterogeneity of MYC may be advantageous for cancers." (PMID 37941901, 2023). "A comparison of the high-SERPINF1 versus the low-SERPINF1 cluster showed that cancer-promoting signaling pathways were significantly enriched, including for Notch signaling, E2F targets, mitotic spindle, G2M checkpoint, wnt/β-catenin signaling, and MYC target pathways." (PMID 36980858, 2023). "Indeed, activation of ERα allows the expression of factors such as MYC, Cyclin D1, FOXM1, GREB1, BCL2 or amphiregulin, IGF-1 and CXCL12, which have oncogenic potential, increasing cancer cells proliferation and the risk of DNA damage in response to the estrogens." (PMID 37047814, 2023). "However, it has been observed that cancers exhibiting elevated MYC expression also demonstrate a global transcriptional amplification linked to increased MYC binding, positive transcription elongation factor b (P-TEFb) recruitment, and release of RNAP2 from pause." (PMID 38117531, 2023). "Overall, MYC may be the most frequently dysfunctional driver gene in cancer." (PMID 37233863, 2023). "In addition, c-MYC is the main regulatory factor for glycolysis in cancer cells." (PMID 37204526, 2023). "For this reason, many therapeutic agents that directly target MYC are under development; however, to date, their clinical efficacy remains to be demonstrated partially due to the extreme difficulty of developing efficient MYC inhibitors specifically targeted for cancer therapy." (PMID 37998757, 2023). "In addition, many studies have shown that SP1, HIF1A, and MYC are often upregulated in cancer." (PMID 37998757, 2023). "However, until now, no direct correlation between MYC transcriptional activities and the cancer‐associated variability of the region has been demonstrated." (PMID 36366788, 2023). "Therefore, the specific factors that collaborate to regulate NE fate in different cancer types may impact the generalizability of MYC-dependent NE fate modulation." (PMID 37255415, 2023). "The transcription factor c-MYC (hereafter MYC) controls expression of numerous genes involved in the proliferation, growth, metabolism and DNA damage responses of normal cells in adult tissues and its deregulated over-expression is a major driver of human cancer." (PMID 36755068, 2023).
cancer (continued). "Co‐inhibition of TAF10 and MYC may thus serve as a novel cancer therapeutic strategy." (PMID 36639831, 2023). "Furthermore, SOX2 stimulated c-MYC expression and enhanced cancer stem-like properties." (PMID 36721232, 2023). "However, recent cancer dependency map studies utilizing CRISPR/Cas9 and small hairpin RNA–based genetic screens may represent valuable resources to identify novel therapeutic opportunities to target MYC-dependent cancer cells." (PMID 37642941, 2023). "A subset of cancer cells under replication stress may be susceptible to ATR inhibitors, as well as other DDR inhibitors, such as CHK1 or WEE1 under MYC- or CCNE1-induced replication stress." (PMID 37422534, 2023). "Moreover, increased FAO in the cancer cells could be linked with various mutations and overexpression of the KRAS and MYC oncogenes, respectively." (PMID 37762231, 2023). "Interestingly with regard to cancer biology and for therapy-related facets, a role for IVNS1ABP in MYC-associated pathways has been reported and a certain degree of association between sensitivity to bromodomain inhibitors and enhanced MYC-signaling has also been described." (PMID 37173708, 2023). "KLF4, a member of the Yamanaka factor family (OCT3/4, SOX2, KLF4, and c-MYC, collectively referred to as OSKM), is known to play a crucial role in embryonic stem cells and is also implicated in maintaining stemness and EMT processes in the context of cancer stem cell models." (PMID 37762678, 2023). "However, it is still not fully understood how MYC impacts these oscillations and how this could support cancer development." (PMID 37639465, 2023). "Notwithstanding the fact that the expression levels of genes involved in the Wnt pathway and EMT process were not influenced, cancer cells surviving the in vivo combinatorial treatment showed a markedly increased expression of MYC levels, regardless of the mutational status." (PMID 35158939, 2022). "Thus, we focused on MYC which was a highly pleiotropic transcription factor with broad effects on cell proliferation, metabolism, angiogenesis, apoptosis, adhesion, and differentiation, whose overexpression was usually related to cancer." (PMID 36120320, 2022). "Collectively, these results implicate MYC, FOX (specifically FOXM1), and BRD family of TFs in the regulation of EP events through upregulation of CSFs and may represent master regulators of broad splicing changes associated with development and cancer." (PMID 36509773, 2022). "Therefore, MYC-driven cancers, including TNBC, are more sensitive to CDK7 inhibition." (PMID 36139513, 2022). "Importantly, MYC is a commonly activated oncogene in human cancer." (PMID 35558067, 2022). "In addition, MYC pathway activation is an extremely common cancer-driving event, suggesting that AS-mediated synthetic lethality may impart therapeutic vulnerability to a large number of cancer types." (PMID 35014671, 2022). "Further investigation into the specific amino acids responsible for the binding of MTBP to Tip48/Tip49 as well as crystallization of this structure may allow for development of potential therapeutics to target MTBP in cancer, as has been accomplished with other MYC cofactors." (PMID 35741402, 2022). "Furthermore, the experimental results suggest that interferon gamma regulated programmed cell death 1 ligand 1 expression through the regulation of MYC, which may further affect the response to PD-1/PD-L1 cancer immunotherapy." (PMID 36582540, 2022). "However, cancer cells can downregulate MYC and proliferation in favor of movement." (PMID 35741402, 2022). "Interestingly, higher sensitivity to splicing inhibition was also observed in MYC-driven cancers." (PMID 35406598, 2022). "However, to date, no study has investigated the potential link between S146L and MYC-driven cancer." (PMID 36018850, 2022).
cancer (continued). "Therefore, MYC-dependent tumors are likely sensitive to the inhibition of nucleolar activity, making the inhibition of excessive ribosome biogenesis in tumors an attractive approach for cancer therapeutics." (PMID 35159381, 2022). "In addition, the c-MYC gene product is known to be a major factor in cancer development." (PMID 36012470, 2022). "Finally, GSEA analysis revealed that ZDHHC7 might impact cancer progression by MYC targets V1/V2, G2M checkpoint, mitotic spindle and E2F targets pathway." (PMID 36286021, 2022). "Interestingly, cancer‐related pathways, such as cell cycle (MYC targets V1) and MTORC1 signalling, were also upregulated in both HCC and CLD samples, suggesting that these pathways may already be transcriptionally dysregulated in the precancerous lesion." (PMID 34863035, 2022). "Additionally, we will discuss the inhibition of cancer cell growth and induction of cancer cell death by decreasing MTBP levels, indicating MTBP may represent a new cancer drug target and a way of indirectly targeting MYC." (PMID 35741402, 2022). "In addition to showing the phenotype in cancer-derived cells, we used siRNA knockdown of MYC and MAPK inhibitor treatments as alternative approaches to validate that depletion of oncogenes and inhibition of their signaling reverses these effects on interferon and ISG expression." (PMID 35594991, 2022). "Therefore, whereas both CDK7 and CDK9 may contribute to cancer cell fitness through differential interactions with the MYC network, they display clearly specialized relationships with other signaling pathways relevant for cancer development." (PMID 36577800, 2022). "However, we found that CIP2A, a protein that is overexpressed in cancers and shown to bind MYC and prevent PP2A from dephosphorylating Ser 6233, was robustly downregulated upon treatment with either YM155 (compare lanes 1 and 2 for each cell line) or siRNAs that target Survivin." (PMID 36581205, 2022). "Specifically, inhibiting these enzymes could decrease c-MYC levels and slow cancer growth." (PMID 35159073, 2022). "However, MYC is one of the most deregulated genes in a variety of cancers." (PMID 36361720, 2022). "In addition to c-MYC, the cell cycle protein cyclin D is another key target in cancer therapy." (PMID 36237336, 2022). "Therefore, the inhibitors of super enhancer might inhibit the cancer cell proliferation, migration and invasion by suppressing the MYC target genes such as CDK6 and TGFβ2." (PMID 35879772, 2022). "Thus, inhibition of OTUB1 may blunt c-MYC activity, making it a promising target for cancer treatment." (PMID 35159073, 2022). "Furthermore, it suggests that cancer cells along the MYC-RAS axis may require distinct profiling approaches and cell line avatars to discover axis-specific therapies." (PMID 35013227, 2022). "In addition, ZEB1 may directly bind and thereby regulate the expression of multiple cancer stem cell markers including MYC and ABCB1." (PMID 35404029, 2022). "In addition, the formation of the MIR100HG/hnRNPA2B1/TCF7L2 forward-regulatory loop and the c-MYC/LINC01234/hnRNPA2B1/miR-106b-5p/Cry2/c-MYc positive-feedback loop could effectively accelerate disease progression in cancer patients." (PMID 35879279, 2022).
cancer (continued). "We recently reported that the essential MYC cofactor TRRAP (Transformation/transcription domain-associated protein) forms a critical interaction within the MYC TAD, which may represent a viable strategy for targeting MYC in cancer by inhibiting MYC:TRRAP binding." (PMID 36018850, 2022). "In addition, the rs6983267 genotype is associated with metastatic risk in IBC but not in nIBC, suggesting that MYC is also involved in cancer cell dissemination in IBC58." (PMID 35042871, 2022). "Furthermore, PDK1 mediates chemoresistance in different cancer cell types by the activation of several oncogenic pathways, namely Polo-like kinase-1 (PLK1)- myelocytomatosis (MYC) Axis, Yes-associated Protein (YAP)/Hippo Pathway, and the serum and glucocorticoid inducible protein kinase (SGK) Axis." (PMID 36076967, 2022). "Therefore, enhanced lncPVT1 level may increase MYC activity in cancer cells by impairing its turnover." (PMID 34754096, 2022). "Furthermore, we identified an EMT gene expression signature with an increase in stemness markers, suggesting that interactions between the clock and MYC could be involved in the progression of CRC by regulating the population of cancer-initiating cells." (PMID 35947664, 2022). "Importantly, phosphorylation cascade is a highly effective strategy for signal amplification, which may explain why RIPK2 and MYC activity scores are strongly correlated in PC and many other cancer types." (PMID 35115556, 2022). "This review summarizes the importance of nucleolar activity in mammalian cells, MYC’s role in nucleolar regulation in cancer, and discusses how a better understanding (and the potential inhibition) of aberrant nucleolar activity in cancer cells could lead to novel therapeutics." (PMID 35159381, 2022). "Therefore, targeting c-MYC is a potential therapeutic strategy for malignant tumors." (PMID 36233342, 2022). "Moreover, MYC dysregulation is commonly observed in multiple human cancers, including HCC." (PMID 34663798, 2021). "Similarly, c-MYC, Pontin and Reptin together, decondense the chromatin at the end of mitosis and increase cell proliferation in Xenopus laevis egg extracts and also in human cancer cells in an ATP-dependent manner." (PMID 33599797, 2021). "Importantly, aberrant P27 accumulation is associated with chromosome instability (CIN; ongoing changes in chromosome numbers) and mitotic defects, whereas aberrant Cyclin E1 and c-MYC turnover lead to cell cycle and apoptotic defects that promote cancer development and progression." (PMID 35008511, 2021). "Therefore, concurrent targeting MYC and HIF1α may represent a better, more effective way for cancer with high expression of MYC and/or HIF1α." (PMID 33572152, 2021). "Therefore, the model may help quantitatively evaluate the potential role of candidate therapies and immune effectors to target MYC and other oncogenes during the process of cancer growth and regression." (PMID 33446671, 2021).
cancer (continued). "Indeed, over the years, new approaches have been identified to develop potent molecules with positive pharmacokinetic profiles, and new mechanistic insights have been gained, thus paving the way toward the development of a truly effective inhibitor in MYC-driven cancers." (PMID 33801599, 2021). "However, whether MYCN in NBL exerts a similar effect on immune regulation as MYC does in other cancers remains to be investigated." (PMID 33668573, 2021). "In addition, previous studies have focused on cancer types where MYC is the main effector target of BET inhibition, and it was unknown whether mechanisms of resistance would be common across diverse cancers where JQ1 suppresses different targets." (PMID 33712563, 2021). "The stemness gene LIN28B promotes cancer stemness and metastatic properties by enhancing glycolysis and lactate secretion, partly through modulating the MYC/miR-34a signaling pathway, suggesting that miR-34a may regulate CSCs through rewiring cancer metabolism." (PMID 33763422, 2021). "In this mini-review, we briefly describe recent progress in understanding MYC control by the ubiquitin proteasome system including novel ubiquitin ligases and deubiquitinating enzymes and then focus on the perspectives of targeting these molecules for cancer therapy." (PMID 34178666, 2021). "Therefore, targeting MYC using CRISPR/Cas9 system may lead to a promising clinical outcome in cancer therapy." (PMID 34199901, 2021). "Therefore, the MYC G4 is considered a promising target for cancer therapeutics." (PMID 33978746, 2021). "Therefore, while MYC is regarded as a universal target in cancer, the identification of MYC-responsive lncRNAs in distinct tumors may represent an alternative strategy for unveiling novel biomarkers as well as driver genes and therapeutic targets." (PMID 34359754, 2021). "Moreover, several findings support an intimate relationship between KRAS and MYC, which seem to cooperate and maybe even act interdependently in cancer cell metabolic reprogramming." (PMID 34503295, 2021). "The prominent increase in enhancers bound by MYC may underscore the relevance of distal regulatory elements in cancer cells, whereby MYC drives their epigenetic remodeling by stimulating the deposition of chromatin-activating marks and may favor promoter–enhancer contacts." (PMID 34201047, 2021). "Beyond the known targets of YAP (i.e., MYC and CCND1), we uncovered TRAM2 (translocation chain-associated membrane 2) and described its contribution to cellular proliferation, epithelial to mesenchymal transition (EMT), and cellular migration and invasion, as well as cancer prognosis." (PMID 33514403, 2021). "Thus, drugs such as BRD4 inhibitors that target the upstream pathways regulating MYC may be attractive candidates to control the metabolism and growth of chemoresistant cancer cells." (PMID 34031395, 2021). "Indeed, the correlation between TERT and MYC is well-documented in various cancers." (PMID 33599797, 2021). "Besides, the over-expression of MYC promoted cancer cell growth in both VCaP and LuCaP-147 cells." (PMID 33531470, 2021). "Therefore, our research is based on the fact that MYC is a recognized key cancer gene." (PMID 33540574, 2021). "However, c-MYC is a proto-oncogene overexpressed in many cancers, including CRC." (PMID 34887764, 2021). "In addition, C-Myc [MYC] is one of the most common inhibitory transcription factors in cancer." (PMID 34778060, 2021).